CHIAP2 (chitinase, acidic pseudogene 2)
Gene: Transcribed unprocessed pseudogene on chromosome 1 (111,280,060 to 111,286,043, forward strand). Ensembl gene ENSG00000203878.
Diseases named in the same sentence as CHIAP2 in open-access papers:
CHIAP2 is named in the same sentence as 4 diseases in open-access papers, as found by Europe PMC text mining. Sharing a sentence is not in itself a finding about the gene and the disease. The quoted sentences say what the papers report.
lung adenocarcinoma (2 papers, 2019 to 2020). A carcinoma that arises from the lung and is characterized by the presence of malignant glandular epithelial cells. "Pseudogene-derived lncRNA, CHIAP2, suppressed lung adenocarcinoma cell proliferation and invasion by modulation of miR-3614-5p and miR-873-3p-mediated inhibition of NFATC2 and GSK3B." (PMID 32185172, 2020). "After upregulation of CHIAP2, the impaired proliferation and invasion of lung adenocarcinoma were observed." (PMID 32185172, 2020).
lung carcinoma (1 paper, 2017). "CHIAP2 was detected in the lung cancer-related ceRNA network." (PMID 29029488, 2017).
CHIAP2 also shares sentences with these, for which no sentence is quoted: cancer (1 paper); tumor (1).